MUC16 (mucin 16, cell surface associated)
Diseases named in the same sentence as MUC16 in open-access papers (continued):
Sharing a sentence is not in itself a finding about the gene and the disease.
cancer (continued). "Together, these findings suggest that truncated O-glycan containing MUC16 exacerbates malignancy in PDAC by activating FAK signaling through specific interactions with α4 and β1 integrin complexes on cancer cell membranes." (PMID 35628269, 2022). "The presence of MUC16 neo‐antigen‐specific T cell clones and anti‐MUC1 antibodies in cancer suggests that MUCINs can serve as potential targets for developing cancer therapeutics." (PMID 34327857, 2021). "Mucin 16 (MUC16), also known as CA‐125, is a transmembrane member of the mucin family and is overexpressed in many types of cancer." (PMID 33543559, 2021). "MUC16, the coding gene of mucin 16, promotes the proliferation and metastasis of cancer cells, and the cancer antigen CA125, as an epitope present on mucin 16, is the most commonly used serum biomarker in epithelial ovarian cancer." (PMID 34568069, 2021). "In this direction, various glycoproteins such as prostate specific antigen (PSA), MUC16, aberrantly glycosylated MUC1 and CA19-9, including others, have been used historically to detect various cancers." (PMID 32075174, 2020). "A statistically significant difference in NPX levels between benign tumors and borderline tumors + cancer was found for only two proteins, HE4 (WFDC2) and CA125 (MUC16) (conservative cut-off p < 0.001, p-values adjusted with False Discovery Rate (FDR))." (PMID 33075095, 2020). "To ascertain the cytotoxicity of CAR-T cells against MUC16 or PDL1 positive cancer cells in vitro, we co-cultured CAR-T cells and cancer cells (1 × 104cells/well) at 1:1, 4:1,8:1, 16:1 ratio." (PMID 32689954, 2020). "Three genes are involved in immune system response to cancer, which clearly indicates that they bear a protective role: PDCD1, KLRG1, and MUC16." (PMID 31568528, 2019). "While there was a negligible reduction in the overall mutational load after filtering highly recurrent variants, the filtering impact was notable for several known cancer-related genes (e.g., ERBB4 and MUC16)." (PMID 31262303, 2019). "Tumor-associated cell surface receptors including CD44, mucin 16 (MUC16), placental cadherin, and various integrins were all shown to mediate initial adhesion of cancer cells to mesothelial cell layers." (PMID 31817625, 2019). "Among MUC family, MUC16 and MUC4 were the top two RMGs identified from most cancer types (17 and 12, respectively)." (PMID 30107644, 2018). "Ca125 (also known as MUC16) is a protein that has a well-established role in the PDAC development, especially in the later stages; for instance, it promotes cancer cells motility and drug-resistance and reprograms PDAC metabolism." (PMID 28356610, 2017). "We observed an exclusively abundant expression of MUC16 and SIRPA in the dysplastic lesions and the corresponding carcinoma tissues of this patient." (PMID 28383029, 2017). "MUC16/CA125 is a high molecular weight TM carrying the CA125 epitope, a well-known molecular marker for human cancers." (PMID 26918940, 2016). "A wide range of adhesion molecules including CD44, CA125/MUC16, ICAM-1 or VCAM-1 are reportedly involved in the binding of cancer cells to the mesothelium." (PMID 26426054, 2015). "3A5 targets MUC16 tandem repeats and is more effective than 11D10 in delivering MMAE to cancer cells and inducing cell death." (PMID 24886523, 2014). "The expression rates in cancer lesions (more than 5% of carcinoma cells stained) were MUC1, 51.7% (31/60); MUC2, 26.7% (16/60); MUC3, 55% (33/60); MUC4, 51.7% (31/60); MUC5AC, 33.3% (20/60); MUC6, 10% (6/60) and MUC16, 8.3% (5/60)." (PMID 24722639, 2014). "The recent study indicated that LGALS3BP, MUC16, SCGN and SLC39A6 had abnormal expression in various cancer." (PMID 22438889, 2012). "The role of mucin in cancer metastasis has been characterized in MUC1 and MUC16." (PMID 40699805, 2025).
cancer (continued). "The binding of AR9.6 to SEA5 of MUC16 interferes with MUC16′s interaction with cell surface receptors of the ErbB family and their downstream signaling pathways through AKT and GSK3β, eventually disrupting cancer growth." (PMID 40149293, 2025). "In summary, MUC1 and MUC16, key molecules within the mucin family, exhibit roles in cancer biology surpassing the conventional barrier formation in normal epithelial cells." (PMID 38361923, 2024). "MUC16 expression supports the proliferation of cancer cells through binding with the non-receptor tyrosine kinase JAK2, which leads to the phosphorylation of the transcription factor STAT3 and activation of c-Jun, responsible for the expression of Cyclin D1." (PMID 39685591, 2024). "From the list of 20 FLAGS (FrequentLy mutAted GeneS) genes that are known to be frequently mutated in cancer but are unlikely to be pathogenic, TTN, AHNAK2, SYNE1, MUC16, and OBSCN were found among genes altered at ≥ 20% in mCLM." (PMID 38008721, 2023). "The immune signaling and cancer pathways were enriched in the MUC16WT group due to the GSEA analysis of LUAD samples with and without MUC16 mutations." (PMID 37932988, 2023). "Another gene, MUC16, also known as CA125, is the gold standard biomarker used to diagnose and monitor ovarian cancer progression and recurrence and has been reported to be overexpressed in several cancers." (PMID 36450891, 2023). "Overall, these results suggest that the interaction between MUC16 and α4β1 integrins increases the migratory ability of PDAC cells, and these interactions are positively regulated by aberrantly glycosylated structures frequently observed in this cancer." (PMID 35628269, 2022). "Additionally, sufficient studies have suggested that SETD2, BAP1, mTOR, MUC16, HMCN1, KDM5C, ARID1A, and PTEN are intimately tied to prognosis and immune response in cancers." (PMID 35936012, 2022). "We hypothesized that the higher, avidity-driven binding affinity for the cancer antigens of the parental PSMA and MUC16 antibodies used to generate these bsAbs would block the target arm’s binding of the bsAbs in a dose-dependent manner." (PMID 34257348, 2021). "For example, while absent in healthy pancreatic tissue, expression levels of MUC16 increase in moderately to poorly differentiated cancers, as is the case of the BxPC3 cell line used." (PMID 32886718, 2020). "TNFα and IFNγ, the two most studied cytokines in that context, have been shown to enhance MUC16 shedding in some but not all cancer cell lines suggesting also a complex regulation of MUC16 expression that is dependent on the cellular context." (PMID 31039761, 2019). "Interestingly, TCI revealed functional impact of certain SGAs with very high alteration frequencies, such as TTN, CSMD3, MUC16, RYR2, LRP1B, and ZFHX4, whose roles in cancer development remain controversial." (PMID 31276486, 2019). "We also analyzed MUC4, MUC16 and MUC20 expression in datasets of other cancers." (PMID 30236127, 2018). "LMB-100 decreased the abundance of 24 of 32 cancer-related proteins (including Bcl-x, Her2, Her3 and MUC16) without compensatory increases in other analytes." (PMID 30384408, 2018). "The expression of MUC16 and SIRPA was barely detectable in the cancer adjacent normal tissues." (PMID 28383029, 2017). "We have previously reported on Meso-TR3, a constitutive TRAIL trimer targeted to the biomarker MUC16 (CA125), in which the entire ectodomain of human mesothelin was genetically fused to the TR3 platform, facilitating attachment to the cancer cells via the MUC16 receptor." (PMID 27120790, 2016).
cancer (continued). "Recently, we and others have shown that MUC16 is overexpressed in PDAC, and the expression increases as cancer progresses from precursor invasive lesions (Pancreatic Intraepithelial Neoplasia (PanIN)) to metastatic PDAC, while it is not detected in the normal pancreas." (PMID 27382435, 2016). "It turned out that the dual-domain biologic Meso64-TR3 retained its high MUC16 affinity and bound to the cancer cells quickly, independent of the TR3/death receptor interaction." (PMID 27120790, 2016). "Functional cell viability data suggested that Meso-TR3 and Meso64-TR3 appeared to have much higher affinity to MUC16-expressing cancer cells than non-targeted TR3." (PMID 27120790, 2016). "While in the number 3 sample, MUC16 did not obviously increase in the carcinoma tissue, and those proteins showed no changes coincidentally." (PMID 27167110, 2016). "Several mucin (MUC) glycoproteins have been shown to be overexpressed during cancer and have therefore been targeted in cancer vaccines, including MUC1, MUC4, MUC5AC, and MUC16." (PMID 26557640, 2015). "Since these cancer cells grow well in soft agar, even in the absence of MUC16 expression, we went directly to the effect of the MUC16c344 on matrigel invasion." (PMID 25965947, 2015). "Soluble Meso-TR3 targets the cancer biomarker MUC16 in vitro and in vivo and exhibits all the positive features of a traditional TRAIL-based cancer drug, as well as enhanced stability, enhanced killing capacity and favorable 1:3 stoichiometry of targeting (mesothelin) and effector domain (TR3)." (PMID 24447304, 2014). "One of the key characteristics of this novel cancer drug is its potency on MUC16-positive cancer cells with reduced killing abilities on MUC16-negative cancer cells." (PMID 24447304, 2014). "VK-8 was used in experiments that ultimately led to the cloning of MUC16 and the OC125 antibody was used as a reagent to establish the clinical-grade CA125 assay to measure the concentration of this marker in the sera of cancer patients." (PMID 20497550, 2010). "ch5E6 did not react to shed MUC16 present in the conditioned media of cancer cell lines, and binding levels to MUC16-Cter did not alter in the presence of a 10-fold excess of clinically detectable quantities of soluble MUC16 antigen, divulging their exclusive therapeutic index." (PMID 37567918, 2023). "Moreover, MUC16 is associated with PDAC malignant progression, and that truncated O-glycans containing MUC16 activate FAK signaling through specific interactions with α4 and β1 integrin complexes on cancer cell membranes, contributing to PDAC malignancy progress." (PMID 37007021, 2023). "MUC16 bearing truncated O-glycans exacerbates malignancy by FAK activation through interactions with integrins on cell membranes, indicating that O-glycans might regulate the localization and turnover of target proteins and be involved in cancer progression." (PMID 35864552, 2022). "Several sialylated proteins have been approved as cancer biomarkers, including prostate-specific antigen (PSA) used for screening of PC, α-fetoprotein used for diagnosis and monitoring of HCC, CA125 that detects the mucin glycoprotein MUC16 in ovarian cancer and thyroglobulin for thyroid cancer." (PMID 33921986, 2021). "Interestingly, CD44-STn contributes to cancer tolerogenic immune responses and cell invasion, whereas MUC16-STn is expressed by subgroups of patients that do not respond to cisplatin-based therapeutics." (PMID 34108014, 2021). "Importantly, truncated O-glycans are selectively found on circulating MUC16 in cancer patients and not in benign conditions." (PMID 30011875, 2018).
cancer (continued). "Finally, Mucin-16 (also known as MUC-16), a transmembrane protein that functions as a barrier to bacterial infections, protects cancer cells from being killed by immune cells and contains the CA125 peptide, demonstrated a nearly 5-fold difference between HPV-positive and HPV-negative tumors." (PMID 29587383, 2018). "In addition, biophysical analyses demonstrated much enhanced thermal stability of Meso64-TR3 over Meso-TR3 on MUC16-positive and -negative cancer cells, acting as a monomer in solution with a preference to eliminate the cells it binds." (PMID 27120790, 2016). "Hence, we evaluated the effect of MUC16 knockdown on PI3K-Akt-mTORC1 pathway, which plays an important role in the regulation of cellular metabolism including glycolysis and plays a very significant role in the progression of several types of cancer." (PMID 26046375, 2015). "Briefly, after correcting for sequence length, the TTN and MUC16 genes did not rank the top 10 for some cancers (e.g., breast, liver, kidney, etc.)any more, implying that their high mutation frequency in these cancers was largely due to their long sequence without a statistical significance." (PMID 26212640, 2015). "In the 108 cases, the positive expression rates (more than 5% of carcinoma cells stained) of each mucin antigen were MUC1, 47.2% (51/108); MUC2, 71.3% (77/108); MUC3, 18.5% (20/108); MUC4, 93.5% (101/108); MUC5AC, 50.0% (54/108); MUC6, 4.6% (5/108) MUC16, 16.7% (18/108) and MUC17, 86.1% (93/108)." (PMID 25551773, 2014). "Furthermore, general up-regulation of MUC1 and MUC16, independent of specific glycan expression, protects Capan-1 cancer cells from ADCC and CTL-mediated killing." (PMID 24039759, 2013). "However, a subset of cancer patients with no elevation in the standard CA 19-9 assay showed elevations of the CA 19-9 antigen specifically on the proteins MUC5AC or MUC16 in all sample sets." (PMID 22220206, 2011). "We found that patients with both MUC16 and TTN mutations had higher mortality risk than patients with neither mutation, and that patients with TTN mutations alone had an even higher mortality risk than patients with neither mutation, which differs from previous cancer literature." (PMID 39240165, 2024). "In order to assess the potential benefit of a MUC16-targeted TR3 variant over its non-targeted counterpart on MUC16-positive cells that are refractory to TRAIL treatment, we took advantage of our recently designed, cancer-targeted small molecule SMAC mimetic SW IV-134." (PMID 27120790, 2016). "The colony formation in SKOV3 wildtype or MUC16+ and OVCAR8 cells showed that lack of ABL1/SYCP2 expression or SYCP2 phosphorylation activity mediated by ABL1 would largely reduce the cancer cell survival." (PMID 40918650, 2025). "Our preliminary data indicates that Ad5/MUC16-1040/TK-EGFP can indeed replicate in and lyse primary cancer cells collected from patients, but not in normal cells as represented by fibroblasts." (PMID 34503075, 2021). "We also found that some of the identified genes, including TTN, MUC16, CSDM3, RYR2, USH2A, and SYNE1, are only altered in gynecological malignancies and not in other cancer types, highlighting their specific role in driving gynecological malignancies." (PMID 32626534, 2020).
infection (15 papers, 2012 to 2026). The state of being infected such as from the introduction of a foreign agent such as serum, vaccine, antigenic substance or organism. "Collectively, these results point to a MUC16 ectodomain release-dependent mechanism utilized by the EKC-causing HAdV-D37 to initiate infection at the ocular surface." (PMID 27303700, 2016). "Since cell invasion is a well-established process of infection, these experiments indicate that a loss in the levels of apical MUC16 on the epithelial barrier enhances internalization, thus infection." (PMID 22412870, 2012). "For example, identified loci near MUC4 and MUC16 were supported by genetic variants that increased mucin expression in cilial lung tissue that might be protective for infection." (PMID 36554876, 2022). "Genetic deletion of Muc16 in mice markedly reduced fungal vascular binding, renal fungal burden, and Ly6Ghi CD11b+ neutrophil recruitment following intravenous infection, and diminished oral colonization in an oral model." (PMID 41836507, 2026). "BALB/c mice were infected with HMPV, and the expression of Muc1, Muc2, Muc4, Muc5ac, Muc5b, Muc15, Muc16, Muc19, and Muc20 were analyzed at 12, 24 and 48 h after infection." (PMID 32899224, 2020). "Additionally, we identified 10 genomic regions associated with breakthrough infection (SLC6A20, ST6GAL1, MUC16, FUT6, MXI1, MUC4, HMGN2P18-KRTCAP2, NFKBIZ and APOC1), and one with breakthrough severity (APOE)." (PMID 39384777, 2024). "MUC16, also known as CA125, is thought to provide a protective lubricating barrier against infectious agents and particles on mucosal surfaces; thus, CA125/MUC16 may represent a marker for infection." (PMID 37762764, 2023). "Observations of the anti-adhesive, barrier properties of MUC16 at the epithelial surface raise an important question about the ability of non opportunistic pathogens, especially the epidemic disease-causing ones, to breach the MAM glycocalyx barrier and trigger infection." (PMID 22412870, 2012). "In contrast, G5P infection decreased expression of transmembrane mucin genes significantly (MUC12, MUC16 and MUC21) or numerically (MUC1, MUC4, MUC13 and MUC20)." (PMID 37848925, 2023). "Utilizing the same detection methods, the infection rates of PD1-antiMUC16 CAR-T cells, PD1 CAR-T cells, and anti-MUC16 CAR-T cells were obtained (52.36, 46.03, and 86.24%, respectively)." (PMID 32689954, 2020). "Clearly, follow-up experiments are needed to understand the mechanistic basis of interactions between HAdV-D37 and MUC16 at the ocular surface and to determine whether a similar MAM ectodomain release strategy is used by adenoviruses to trigger infections at other mucosal surfaces." (PMID 27303700, 2016). "Compared to uninfected cells, HMPV infection induced a significant fold-increase expression of MUC1 (8.3 ± 2), MUC2 (43.4 ± 13), MUC4 (54 ± 12), MUC5ac (23.3 ± 11.5) and MUC19 (77 ± 35), while no significant induction of MUC15, MUC16 and MUC20 was observed." (PMID 32899224, 2020).
adenocarcinoma (14 papers, 2011 to 2025). A common cancer characterized by the presence of malignant glandular cells. "CA125 is an epitope on Mucin-16 (MUC16), a massive (>22,000 amino acids) membrane-bound glycoprotein that is normally expressed in the epithelium of the endometrium, trachea, and cornea and is often upregulated in adenocarcinomas." (PMID 35628269, 2022). "CA125 is currently considered to be MUC16, and its amino acid sequence has some properties of mucin molecules, which may have better clinical application in adenocarcinoma." (PMID 30863466, 2019). "While the expression of MUC16 was not significantly different between the three groups, the mean composite score was significantly higher in moderate and poorly differentiated PC compared to well-differentiated adenocarcinomas (p = 0.02 and 0.001 respectively)." (PMID 22066010, 2011).